LRRK2 (leucine rich repeat kinase 2)
Diseases named in the same sentence as LRRK2 in open-access papers (continued):
Sharing a sentence is not in itself a finding about the gene and the disease.
Parkinson disease (continued). "PD risk genes such as DJ-1, PINK1, PRKN, and LRRK2 share mitochondrial dysfunction, and 1-methyl-4-phenyl-1,2,3,6-tetrahydropyridine, a complex I inhibitor, induces parkinsonism, which is frequently used in PD mouse models." (PMID 40149582, 2025). "The most common cause of familial Parkinson’s disease is linked to mutations in the leucine rich-repeat kinase 2 (LRRK2) protein that phosphorylates Rab10, Rab8a, Rab12 and Rab35." (PMID 40801573, 2025). "As a result of genetic studies, LRRK2 is thought to be associated with Parkinson's disease, Crohn's disease, multibacillary leprosy, and cancer." (PMID 39897276, 2025). "Genetic predispositions to heightened fatigue risk in Parkinson's disease patients are also attributed to genes such as leucine-rich repeat kinase 2 and glucocerebrosidase beta mutations." (PMID 40276401, 2025). "Activating mutations in Leucine Rich Repeat Kinase 2 (LRRK2) are a major cause of inherited Parkinson’s disease." (PMID 40463289, 2025). "The search focused on publications from the past 25 years (2000-2025), using combinations of key terms such as “Parkinson’s disease”, “PD biomarkers”, “alpha-synuclein”, “LRRK2”, “DJ-1”, “miRNAs”, and “polygenic risk score”." (PMID 41050048, 2025). "We show that GPNMB is secreted in response to lysosomal stress via lysosomal exocytosis and highlight the Parkinson's disease risk factor LRRK2 as a strong modulator of GPNMB secretion." (PMID 41406229, 2025). "Among the LRRK2-associated parkinsonism cases, 46 (31%) were CSFasynSAA- and 102 (69%) were CSFasynSAA+." (PMID 39108519, 2024). "Mutations in the leucine-rich repeat kinase 2 (LRRK2) gene have been widely linked to Parkinson’s disease, where the G2019S variant has been shown to contribute uniquely to both familial and sporadic forms of the disease." (PMID 38644975, 2024). "Mutations in Lrrk2 is a risk factor for Parkinson’s disease and Crohn’s disease, both of which are driven by innate immune responses to gut organisms." (PMID 38440723, 2024). "Individuals with either LRRK2 or biallelic PRKN variants were more likely to report a first-degree relative with Parkinson’s disease, likely attributed to higher penetrance of these gene variants." (PMID 39074992, 2024). "The association of increased LRRK2 kinase activity with both the familial and sporadic forms of Parkinson’s disease has led to an intense interest in determining its cellular function." (PMID 38876305, 2024). "The involvement of genetic variants within LRRK2 (leucine rich repeat kinase 2) has been suspected, as the gene is implicated in Parkinson’s disease (PD) pathogenesis, but this evidence is inconclusive." (PMID 38334615, 2024). "Expression of SNCA and leucine-rich repeat kinase 2 (LRRK2) with known genetic association to Parkinson’s disease was also significantly elevated in microglia from Parkinson’s disease/Lewy body dementia patients." (PMID 37671615, 2024). "In this large sample of individuals with LRRK2-associated parkinsonism, we compared clinical, imaging and biofluid biomarker, and genetic characteristics among those with evidence of CSF asyn aggregates compared to those without." (PMID 39108519, 2024). "MMP8 inhibitors can also mitigate neuroinflammation in a Parkinson’s disease model with LRRK2 G2019S mutation." (PMID 38419037, 2024). "Taking together data from published case series, approximately 22% of LRRK2 associated parkinsonism cases demonstrate neuropathological findings of hyperphosphorylated tau, as occurs in PSP7." (PMID 39108519, 2024). "Nevertheless, it remains possible that CSFasynSAA- LRRK2 parkinsonism cases are at risk for greater cognitive dysfunction." (PMID 39108519, 2024). "Functional genetic variants in Leucine-rich repeat kinase 2 (LRRK2) are the largest known genetic contributor to Parkinson's disease, and these variants also increase the risk of Crohn's disease." (PMID 39883213, 2024).
Parkinson disease (continued). "Mutations in the leucine-rich repeat kinase 2 (LRRK2) gene are linked to both late-onset familial and sporadic forms of Parkinson’s disease (PD)." (PMID 38644975, 2024). "Of note, TXNIP knockdown rescued α-synuclein oligomers in LRRK2 p.Gly2019Ser knock-in 3D organoids, suggesting the importance of this gene in the development of LRRK2-associated Parkinson’s disease." (PMID 39273694, 2024). "LRRK2 has been priorly implicated in Parkinson's disease and has been noted to have an effect on dopamine receptor trafficking." (PMID 39722687, 2024). "The LRRK2 G2019S variant is the most common cause of monogenic Parkinson’s disease (PD); however, questions remain regarding the penetrance, clinical phenotype and natural history of carriers." (PMID 38804604, 2024). "We previously showed that Parkinson’s disease-causative mutations in LRRK2 and SYNJ1 alter synaptic autophagy." (PMID 37067454, 2024). "The analysis comparing risk variants was confined to LRRK2-parkinsonism cases of European ancestry (n=130) of which 48 were CSFasynSAA- and 82 were CSFasynSAA+." (PMID 39108519, 2024). "In human midbrain organoids bearing a Parkinson-driving LRRK2 mutation, a novel Nurr1 agonist rescued tyrosine hydroxylase expression highlighting the potential of the new Nurr1 modulator chemotype as lead and as a chemical tool for biological studies." (PMID 38951694, 2024). "Mutations in the leucine-rich repeat kinase 2 (LRRK2) are the most common genetic cause of Parkinson’s disease." (PMID 38554150, 2024). "We propose that LRRK2 G2019S promotes intestinal inflammation, creating an inflammatory microenvironment conducive to the development of colorectal cancer observed in patients with LRRK2 G2019S-associated Parkinson’s disease." (PMID 38607004, 2024). "We show that LRRK2 G2019S, which is one of the most common known mutations causing Parkinson’s disease, subtly affects axonal function and the injury response." (PMID 38275734, 2024). "Individuals with LRRK2-associated parkinsonism uniformly demonstrate neuronal degeneration in the substantia nigra and locus coeruleus, but the underlying proteinopathy is variable." (PMID 39108519, 2024). "In a Central Asian study of an early-onset Parkinson’s disease population in Kazakhstan, pathogenic mutations were found in only 6% of cases and only in the LRRK2 and PRKN genes, confirming regional differences between populations." (PMID 38397244, 2024). "4E-BP has also been shown to be inhibited by dominant mutations in LRRK2, the most common cause of parkinsonism." (PMID 38397070, 2024). "Asymptomatic Leucine-Rich Repeat Kinase 2 Gene (LRRK2) carriers are at risk for developing Parkinson's disease (PD)." (PMID 38729969, 2024). "Among LRRK2-associated parkinsonism cases with nigral degeneration, over two-thirds demonstrate evidence of pathologic alpha-synuclein, but many do not." (PMID 39108519, 2024). "Activating leucine-rich repeat kinase 2 (LRRK2) mutations cause Parkinson’s and phosphorylation of Rab10 by pathogenic LRRK2 blocks primary ciliogenesis in cultured cells." (PMID 39088390, 2024). "Roco proteins entered the limelight after mutations in human LRRK2 were identified as a major cause of familial Parkinson’s disease." (PMID 38666771, 2024). "Polymorphisms in Lrrk2 are associated with Parkinson’s disease (PD) and Crohn’s disease (CD), both of which are triggered by an excessive innate immune response to intestinal microorganisms." (PMID 38440723, 2024). "Activating mutations in leucine-rich repeat kinase 2 (LRRK2) cause Parkinson’s and block primary cilia formation in specific cells in the mouse brain." (PMID 39088390, 2024). "LRRK2 mutation status impacts the extracellular miRNA signature measured in plasma and separates mutation carriers from sporadic Parkinson’s disease patients." (PMID 38848197, 2024). "Mutations in human LRRK2 are commonly linked to Parkinson’s disease, indicating its important role in regulating basal ganglia function." (PMID 37684522, 2024).
Parkinson disease (continued). "Leucine-rich repeat kinase 2 (LRRK2) mutations are among the most frequent genetic causes of both familial and sporadic Parkinson's disease (PD)." (PMID 39500355, 2024). "Pathological mutations in the Leucine-Rich Repeat Kinase 2 (LRRK2) gene are the most common genetic cause of Parkinson’s disease." (PMID 39062128, 2024). "We measured expression levels of 91 miRNAs via RT-qPCR in ten individuals with sporadic Parkinson’s disease, ten LRRK2 mutation carriers and eleven healthy controls using both plasma and cerebrospinal fluid." (PMID 38848197, 2024). "A higher female prevalence of the LRRK2 mutation suggests a role of gender-related risk factors in Parkinson’s patients, particularly those carrying the G2019S mutation." (PMID 38933683, 2024). "In this study, we used induced pluripotent stem cells derived from a patient with Parkinson’s disease carrying the LRRK2 G2019S mutation and an isogenic gene-corrected control to generate human dopaminergic neurons." (PMID 39726830, 2024). "Up to 4 follow-up visits (after baseline) were expected for 141 LRRK2-associated parkinsonism cases; the majority completed year 4 (31 (69%) CSFasynSAA- and 78 (81%) CSFasynSAA+ cases)." (PMID 39108519, 2024). "Leucine-rich repeat kinase 2 (LRRK2) inhibition is a promising disease-modifying therapy for LRRK2-associated Parkinson’s disease (L2PD) and idiopathic PD." (PMID 39705401, 2024). "Approximately 5-10% of familial Parkinson’s disease cases are attributed to LRRK2 mutations, such as N1437H, R1441, Y1699C, and G2019S." (PMID 38987252, 2024). "Our study provides a unique, genetically stratified cause of Parkinson's disease that is distinct from LRRK2 and is likely to both benefit from and provide unmet insight into LRRK2 function and inhibitor testing within the clinic." (PMID 38614108, 2024). "Mutations in LRRK2 that lead to constitutive activation of its kinase domain are genetically linked to Parkinson's disease and are associated with mitochondrial health and impaired mitophagy." (PMID 38614108, 2024). "Mutations in the human LRRK2 gene are associated with Parkinson’s disease, which is characterized by prominent impairment in dopamine signaling and basal ganglia function." (PMID 37684522, 2024). "Genetic variants in the LRRK2 gene have been linked to both familial and sporadic forms of Parkinson’s disease." (PMID 39726830, 2024). "The G2019S mutation in LRRK2 (encoding leucine-rich repeat kinase 2) is among the most common genetic risk mutations for familial and sporadic Parkinson’s." (PMID 39328984, 2024). "The RAB GTPases are regulators and substrates of LRRK2, and variants in the LRRK2 gene are important risk factors for Parkinson's disease." (PMID 38614108, 2024). "Within the kinase domain of LRRK2, a point mutation known as LRRK2 G2019S has emerged as the most prevalent variant associated with Parkinson’s disease." (PMID 38607004, 2024). "Among individuals diagnosed with Parkinson disease with pathogenic variants in the LRRK2 gene, we found clinical and biomarker differences in cases without versus with in vivo evidence of CSF alpha-synuclein aggregates." (PMID 39108519, 2024). "Pathogenic variants in LRRK2 are one of the most common genetic risk factors for Parkinson’s disease (PD)." (PMID 38854119, 2024). "This suggests an elevated risk of Parkinson’s disease due to LRRK2 mutations, stemming from the impairment of the lysosomal degradation." (PMID 38987252, 2024). "Mutations in the Leucine Rich Repeat Kinase 2 gene are highly relevant in both sporadic and familial cases of Parkinson’s disease." (PMID 38848197, 2024). "Although LRRK2 is a gene associated with Parkinson’s disease, it has also been shown to regulate the function of vascular endothelial cells and promote inflammation in endothelial cells." (PMID 39054468, 2024). "While LRRK2 is a monogenic causative gene for Parkinson’s disease, several mutations have also been suggested to be associated with PSP." (PMID 37264457, 2023).
Parkinson disease (continued). "In Parkinson’s disease, several pathogenic LRRK2 variants, such as G2019S and R1441C/G, have been linked to an increased risk of developing this disease." (PMID 37443813, 2023). "The LRRK2 is a kinase whose mutations have been associated with the development of Parkinson’s disease." (PMID 38196993, 2023). "Hyperactive, pathogenic mutations in Leucine Rich Repeat Kinase 2 (LRRK2) represent the most common cause of inherited Parkinson's disease." (PMID 37889931, 2023). "Overall, these results highlight a new, Rab12-dependent mechanism that results in enhanced activity at the lysosomal membrane with variants associated with Parkinson’s disease, and for LRRK2 in general when lysosomes are damaged." (PMID 37874617, 2023). "Considerable attention has focused on the kinase activity of LRRK2 due to the fact that multiple Parkinson’s disease mutations increase this activity." (PMID 37487100, 2023). "For instance, many genes associated with an increased risk of developing Parkinson’s disease code for proteins required for lysosomes to work properly, such as the kinase LRRK2." (PMID 37874617, 2023). "While all three of these markers are known to be associated with the development of Parkinson’s, the LRRK2 marker seems to be the most highly associated with the onset of the disorder." (PMID 37811009, 2023). "A number of familial Parkinson’s mutations increase autophosphorylation of LRRK2, possibly an indicator of its kinase activity." (PMID 37566051, 2023). "Structures of Parkinson’s Disease-linked LRRK2 bound to inhibitors provide insights for the design of small molecule therapeutics." (PMID 38039358, 2023). "For instance, LRRK2 gene mutations increase the risk of developing Parkinson's disease with a late onset and less severe phenotype, whereas PARK2 gene mutations are associated with early onset and a more severe phenotype." (PMID 37841347, 2023). "Mutations in the LRRK2 gene have been identified as a genetic risk factor for several diseases, including Parkinson’s disease and CD." (PMID 37443813, 2023). "Leucine‐rich repeat kinase 2 (LRRK2) mutation is a common genetic risk factor of Parkinson's disease (PD)." (PMID 36624932, 2023). "Considering that the genetic variation in LRRK2 enhances susceptibility to the second most common neurodegenerative disorder, Parkinson’s disease, these findings render Rab10 signaling pathways as the common mechanisms of neurodegeneration." (PMID 37156612, 2023). "The LRRK2 G2019S pathogenic mutation causes LRRK2-associated Parkinson’s disease (L2PD) with incomplete penetrance." (PMID 36732514, 2023). "Overexpression of a human mutant form of LRRK-2 (leucine-rich repeat kinase 2) involved in Parkinson’s disease causes accumulation of Arl8- and Rab3-positive vesicles at the terminal end of axons, leading to defects in axonal transport." (PMID 37443788, 2023). "Here, we show that LRRK2, a protein that is tightly linked to Parkinson’s disease, negatively regulates lysosome degradative activity in macrophages and microglia via a transcriptional mechanism." (PMID 37487100, 2023). "The most common genetic cause of Parkinson’s disease involves mutations of the Leucine-rich repeat kinase 2 (LRRK2) gene." (PMID 37106761, 2023). "Pathogenic, hyperactive LRRK2 (Leucine Rich Repeat Kinase 2) kinase is strongly linked to Parkinson’s disease and LRRK2 phosphorylates a subset of Rab GTPases that are master regulators of membrane trafficking." (PMID 37889931, 2023). "LRRK2 (Leucine-rich repeat kinase 2) is one of the most frequently mutated genes in familial Parkinson’s disease." (PMID 37844218, 2023). "Much of the interest in LRRK2 derives from mutations in the LRRK2 gene being the most common genetic cause of Parkinson's disease, and from the association of the LRRK2 locus with a number of other human diseases, including inflammatory bowel disease." (PMID 37698513, 2023).
Parkinson disease (continued). "On the other hand, mice bearing the G2019S mutation in the LRRK2 gene (G2019S mice) show Parkinsonism with behavioral and neurochemical DA alterations only at an old age26–30." (PMID 37029193, 2023). "It further demonstrates that a Parkinson’s disease mutation that hyperactivates LRRK2 kinase activity limits the degradative activity of lysosomes more strongly." (PMID 37487100, 2023). "Rab12 regulates LRRK2 activation basally and in response to lysosomal damage and genetic variants associated with Parkinson’s disease (PD)." (PMID 37874617, 2023). "The leucine-rich repeat kinase 2 (LRRK2) gene is a prominent pleomorphic risk locus for Parkinson’s disease (PD), a devastating neurodegenerative disease with debilitating motor and non-motor symptoms." (PMID 37133994, 2023). "Various other LRRK2 mutations such as G2385R, R1628P, S1647T, R1398H, and N551K have also been associated with parkinsonism within certain Asian populations." (PMID 37445986, 2023). "Another study that corrected LRRK2 mutations revealed both LRRK2-dependent and LRRK2-independent effects that are probably genetically influenced and connected to different familial Parkinson’s disease clinical presentations." (PMID 38031028, 2023). "Coding variants in LRRK2 can cause monogenic Parkinson’s disease (PD), and coding and non-coding variants in LRRK2 are associated with increased risk for developing sporadic PD and Crohn’s disease." (PMID 37874617, 2023). "Mutations in leucine-rich-repeat kinase 2 (LRRK2) are common in immune-related disorders, such as inflammatory bowel disease and Parkinson’s disease." (PMID 36986550, 2023). "Parkinson’s disease-associated LRRK2 mutations enhance neuroinflammatory responses, increasing dopaminergic neuron loss and motor deficits." (PMID 38188026, 2023). "The gene mutations of LRRK2, which encodes leucine‐rich repeat kinase 2 (LRRK2), are associated with one of the most prevalent monogenic forms of Parkinson's disease (PD)." (PMID 37672887, 2023). "We reported here that FL090, acting as an LRRK2 kinase inhibitor, ameliorated motor behavioral deficits and rescued the dopaminergic neuron loss in both intoxicated and α‐syn‐related parkinsonism rodent models." (PMID 38020716, 2023). "A meta-analysis showed that Parkinson’s disease patients have a high risk of getting Melanoma, and a subsequent genomic study confirmed the mutation of LRRK2 is associated with Melanoma." (PMID 36562724, 2023). "TH, the rate-limiting enzyme in DA synthesis, has been shown to have decreased protein levels or decreased activity in models of Parkinson’s disease carrying mutations in LRRK2, SNCA, DJ-1 and PINK1." (PMID 36864664, 2023). "Whole genome sequencing identified three amino acid mutations previously associated with Crohn’s disease and Parkinson’s disease as candidate variants for early onset leprosy: LRRK2 N551K, R1398H and NOD2 R702W." (PMID 36972292, 2023). "PPM1H phosphatase reverses Parkinson’s disease-associated, Leucine Rich Repeat Kinase 2-mediated Rab GTPase phosphorylation." (PMID 37889931, 2023). "LRRK2 co-localizes with MTs in cells, forming MT-associated LRRK2 filaments, an association enhanced by Parkinson’s disease mutations." (PMID 37106761, 2023). "Activating mutations in the large, multidomain, leucine-rich repeat kinase 2 (LRRK2) cause inherited Parkinson’s disease and lead to the phosphorylation of a subset of Rab GTPases, particularly Rab8A and Rab10." (PMID 37874635, 2023). "Mutations in LRRK2 (encoding leucine‐rich repeat kinase 2 protein, LRRK2) are the most common genetic risk factors for Parkinson's disease (PD), and increased LRRK2 kinase activity was observed in sporadic PD." (PMID 38020716, 2023). "In this context, our research group identified relations of the Lrrk2 gene, until then associated with Parkinson’s and inflammatory bowel diseases, in preference behavior and loss of control by alcohol in mice, Zebrafish, and humans." (PMID 37063320, 2023).